IL6 (interleukin 6)
Diseases named in the same sentence as IL6 in open-access papers (continued):
Sharing a sentence is not in itself a finding about the gene and the disease.
primary biliary cholangitis (7 papers, 2017 to 2025). Primary biliary cholangitis (PBC) is a chronic and slowly progressive cholestatic liver disease of autoimmune etiology characterized by injury of the intrahepatic bile ducts that may eventually lead to liver failure. "For example, a study in patients with primary biliary cirrhosis revealed the increased levels of IL-1β, IL-6, and TNF-α in such patients compared to healthy controls." (PMID 28299346, 2017). "On multivariate analysis of factors related to the rate of platelet increase with PSE, primary biliary cholangitis (B = 0.475, P < .01), splenic embolization ratio (B = 0.75, P < .01), IL-6 change ratio (B = 0.019, P < .01), and PAIgG change ratio (B = −0.325, P < .01) were significant." (PMID 36221332, 2022).
progeria (7 papers, 2015 to 2024). "As shown, IL6 protein level was significantly increased in the heart, spleen and kidney tissues of progeria mice, which was recovered to a comparable level to that in WT after the DOX feeding." (PMID 38686927, 2024). "Collectively, our study uncovers that DOX can decelerate aging in progeria mice via counteracting IL6 expression and NAT10‐mediated acetylation of α‐tubulin." (PMID 38686927, 2024). "Consistent with previous results, Btg2, p21, IL6, Mmp12, and Atl3 were significantly downregulated by the dCas9‐Oct4 activator in these tissues of progeria mice." (PMID 36964992, 2023). "This theory is supported by the finding that, in the SAMP8 mouse strain (a progeria model), spleen weight and CRP levels were associated with a reduction in IL-6 and IL-6R expression in bone tissues as compared to a wild type control strain." (PMID 36458163, 2022). "Accordingly, elevated expression of TNF-α and IL-6 by the over-activation of NF-κB has been proven to occur in both physiological aging and in progeria human diseases." (PMID 30631004, 2019). "We validated the increased secretion of IL‐6 in progeria cells by ELISA (AG01972, 10‐fold by comparison to WT)." (PMID 31152494, 2019). "Consistent with previous studies, we observed that IL6 secretion is increased in HGPS fibroblasts carrying the classical G608G LMNA mutation and also in fibroblasts from Mandibuloacral Dysplasia, another LMNA‐linked progeroid syndrome." (PMID 33393189, 2021). "Doxycycline decelerates aging in progeria mice and alleviates cell senescence in Zmpste24 KO MEFs and HGPS fibroblasts, probably via counteracting IL6 expression and NAT10‐mediated tubulin acetylation." (PMID 38686927, 2024). "We examined a larger set of inflammatory cytokines in an additional progeria cells (AG03513) after transient expression of hTERT and found reduced mRNA levels of IL6, IL8, IL1B, and GM‐CSF." (PMID 31152494, 2019). "In both progeria and NHDF cells, IL-6 production was upregulated on VZV infection in a time-dependent manner." (PMID 26473290, 2015). "Compared to wild type (WT) mice, the serum level of IL6 in progeria mice was 6.3 times increased, which was then notably decreased upon DOX treatment." (PMID 38686927, 2024).
prostate adenocarcinoma (7 papers, 2017 to 2022). "FOXQ1 expression activated the following pathways in prostate adenocarcinoma: the IL6/JAK/STAT3 signaling pathway, interferon–alpha response pathway, UV response pathway, apoptosis pathway, and allograft rejection pathway." (PMID 36118871, 2022). "CYP1B1High prostate adenocarcinoma patients displayed higher IL6 levels than CYP1B1Low prostate adenocarcinoma patients, and coexpression of CYP1B1 and IL6 was found in PCa tissues and PCa cell lines." (PMID 35292057, 2022). "Among them, IL-1β, IL-6, and CXCL1 have been reported to be factors of immune suppressive SASP that attract myeloid-derived suppressor cells (MDSCs) to inhibit cytotoxic NK and T cell responses in prostate adenocarcinoma." (PMID 36330438, 2022). "WISP1v1 induced IL-6 and CXCL5 in vivo, suggesting that WISP1v1 might be involved in the pro-inflammatory environment of prostate adenocarcinoma in vivo." (PMID 36232736, 2022). "The prostate adenocarcinoma cell line PC3 is STAT3 negative, whereas DU145 has constitutively activated pSTAT3, most probably due to an autocrine production of IL6." (PMID 28636670, 2017).
pseudoexfoliation glaucoma (7 papers, 2015 to 2025). "Earlier, we showed that elevated IOPs were significantly correlated with the intracameral levels of IL-5, IL-6, IL-8, IL-10, IL-15, IL-17, and CCL2 in eyes with pseudoexfoliation glaucoma." (PMID 40353220, 2025). "They found IL-6 and NO levels in aqueous humor were higher in patients with PEX and pseudoexfoliative glaucoma (PEXG) than in controls." (PMID 25713742, 2015).
Psoriasiform dermatitis (7 papers, 2016 to 2025). A skin abnormality characterized by redness and irritation, with thick, red skin that displays flaky, silver-white patches (scales). "Two studies reported increased level of IL-6 after nivolumab treatment was associated with psoriasiform dermatitis in patients with malanoma." (PMID 34367136, 2021). "Topical genistein ameliorated the murine IMQ-induced psoriasiform dermatitis with the reduction of skin score, epidermal thickness, and of IL-1β, IL-6, TNF-α, CCL2, IL-17, and IL-23 expression in the skin lesions." (PMID 32751360, 2020). "Indeed, mast cells were previously demonstrated to play a critical role in the first stages of psoriasiform dermatitis in promoting keratinocyte proliferation and recruiting immune cells through secretion among others of IL6, and TNF." (PMID 27050272, 2016). "Interestingly, high IL6 and TNF expression were often associated with psoriasiform dermatitis." (PMID 27050272, 2016). "Furthermore, PD-1 blockade-induced psoriasiform dermatitis is histologically characterized by prominent epidermal infiltration of CD8+ T cells and overexpression of IL-6, IL-23, and IL-17A cytokines." (PMID 40936709, 2025).
rheumatic heart disease (7 papers, 2019 to 2024). An autoinflammatory condition following an infection with Group A Beta Hemolytic Streptococcus (GABHS), in which the heart is attacked by antibodies formed in reaction to a recent GABHS infection. "Patients with rheumatic heart disease exhibit elevated levels of circulating interleukin-6 (IL-6); IL-8, IL-2 receptor (IL-2R) and tumor necrosis factor α (TNFα)." (PMID 39202692, 2024). "So, we sought to study the effect of LAP on the inflammatory markers, CRP and IL-6, in patients with chronic rheumatic heart disease." (PMID 33638745, 2021). "However another study, conducted on patients of rheumatic heart disease (RHD) in Pakistan reported, significant susceptibility to RHD in the GG mutants of IL-6-174G>C." (PMID 30635365, 2019). "Additionally, in rheumatic heart disease, overexpression of S1PR1 reduces p-STAT3 levels and Th17-associated cytokines RORγt, IL-6 and IL-17." (PMID 37858140, 2023). "In rheumatic heart disease, miR‐155 aggravated the valve injury through S1PR1, SOCS1/STAT3 and IL‐6/STAT3 signalling pathways." (PMID 33664937, 2021). "C-reactive protein and interleukin-6 mean levels were significantly higher in patients with rheumatic heart disease not taking long-acting penicillin compared to patients with rheumatic heart disease taking long-acting penicillin and to the control group." (PMID 33638745, 2021).
rotator cuff tears (7 papers, 2020 to 2025). "Studies involving the Chinese subpopulation with rotator cuff tears (RCTs) have shown the independent impact of IL-6 SNP." (PMID 38732195, 2024). "This partially contradicts the findings of others, showing a rather increased expression of pro-inflammatory factors like SDF1, IL-1β, TNF-α or IL-6 in the bursae of patients with a rotator cuff tear or frozen shoulders." (PMID 38201221, 2023). "Expression of proinflammatory cytokines, such as interleukin (IL)-6 (IL-6) and metalloproteases, are elevated in patients with rotator cuff tear (RCT)." (PMID 32270859, 2020). "Likewise, clinical specimens from patients with rotator cuff tears exhibit upregulation of TNF-α, IL-1β, and IL-6 in the subacromial bursa, implicating these cytokines in pain generation and chronic inflammation inflammatory cytokine." (PMID 40728980, 2025). "The authors found significantly elevated levels of IL-1β, IL-6, tumor necrosis factor (TNF-α), inducible nitric oxide synthase (iNOS), cyclooxygenase-2 (COX-2), and vascular endothelial growth factor (VEGF) in synovial tissue of shoulders with full-thickness rotator cuff tears." (PMID 32821573, 2020).
tendinitis (7 papers, 2013 to 2025). Inflammation of a tendon, usually resulting from an overuse injury. "Regarding the molecular process of tissue repair in tendinitis, interleukin-6 (IL-6) is an acute-phase pro-inflammatory cytokine; however, it can persist late in inflammatory processes, assuming an immunomodulatory function, and is related to tendon healing." (PMID 41463030, 2025). "In-vivo studies have documented increased intratendinous IL-6 concentrations in naturally occurring human tendinitis and experimental rat models of tendinitis." (PMID 37993850, 2023). "In addition, the local injection of SIM/PMSs into the tendons of collagenase-induced Achilles tendinitis rat models suppressed pro-inflammatory cytokines (MMP-3, COX-2, IL-6, TNF-α, and MMP-13)." (PMID 29534523, 2018). "In order to investigate the in vivo anti-inflammatory effects of SIM/PMSs on collagenase-induced Achilles tendinitis models, we monitored the mRNA levels of both pro-inflammatory cytokines (MMP-3, COX-2, IL-6, TNF-α, and MMP-13) and anti-inflammatory cytokines (IL-4, IL-10, and IL-13)." (PMID 29534523, 2018).
typhoid fever (7 papers, 2013 to 2025). A bacterial infectious disorder contracted by consumption of food or drink contaminated with Salmonella typhi. "In the typhoid fever group, IL-2 was equally strongly and positively correlated to IL-6 (r = −0.464, p = 0.01)." (PMID 40014608, 2025). "Consistent with the literature on typhoid fever, levels of IL-6, IL-8, IL12p70 and IFN-γ were significantly increased in patients compared to controls." (PMID 28749963, 2017). "In contrast, the production capacity of pyrogenic cytokines (TNF, IL-6) was depressed in the acute phase of typhoid fever but was restored during the convalescent phase." (PMID 25386175, 2014). "For example, serum IL-6 levels are elevated in patients with typhoid and have been correlated with prolonged fever." (PMID 23754944, 2013). "Similarly, decreased levels of inflammatory mediators, including IFN-γ and IL-17 and TNF-α and IL-6 have been reported in the serum of humans with acute typhoid." (PMID 33076485, 2020). "In the case of typhoid fever, pro-inflammatory cytokines, including IFN-γ, IL-6, IL-10, TNF-α, and TNF, are also produced in large amounts." (PMID 40014608, 2025). "Regarding CMI, as reported in typhoid fever, elevated serum levels of IFN-γ, IL-6, TNF-R p55, and TNF-R p75 were reported in S. Paratyphi A-infected patients." (PMID 25386175, 2014).
vaginitis (7 papers, 2011 to 2025). A non-infectious or infectious inflammatory process affecting the vagina. "Previous studies have shown that proinflammatory cytokines such as TNF-α, IL-1β, and IL-6 are increased in the vagina of women with vaginitis and are associated with the severity of vaginitis." (PMID 39941110, 2025). "GV infection caused vaginitis, increasing uterine weight and TNF-α, IL-6, and RANKL levels, along with increasing the number of NF-κB+ and TNF-α+ cells in the vagina." (PMID 40284791, 2025). "A cross-sectional study demonstrated that serum Vitamin D levels were negatively correlated with IL-6 in patients with recurrent vaginitis." (PMID 37764381, 2023). "Furthermore, vaginal administration of lactoferrin plays a role in reducing the risk of preterm birth for women with shortened cervical length and elevated interleukin 6 levels, being especially effective for women with refractory vaginitis recurring preterm delivery." (PMID 27527166, 2016). "Just like previously seen in VK2/E6E7 cells, VLC infection also caused significant increase in inflammatory markers including IL-6, IL-8, and IP-10 suggesting vaginitis which is again consistent with tissue lesions seen in non-human primates." (PMID 36731656, 2023).
vascular occlusion (7 papers, 2015 to 2025). "After vascular occlusion, IL-1 and IL-6 expression increases, and they act on vascular endothelial cells to express ICAM-1 and selectins, causing leukocyte aggregation and adhesion, and mediating the inflammatory cascade to worsen cerebral ischemic injury." (PMID 36145501, 2022). "There was a significant increase of IL-6 levels in the vascular occlusion group in comparison to control (SMD = 1.68, 95% CI 1.29–2.07, P < 0.00001)." (PMID 33060644, 2020). "After vascular occlusion, the upregulation of cytokines including IL-1 and IL-6 promotes the expression of ICAM-1, P-selectin, and E-selectin in the vascular endothelium, and these inflammatory signals further promote vascular endothelium dysfunction." (PMID 26024305, 2015). "Furthermore, BFR training could cause fine microvascular damage (supported by the slight elevations in IL-6 observed after vascular occlusion) which may trigger local thrombosis." (PMID 38137671, 2023). "Funnel plots and statistical tests (for overall, ocular inflammation, DR, MO, vascular occlusion and AMD: PEgger’s test < 0.05) provided evidence for substantial publication bias, as there were several studies with a large concentration of IL-6." (PMID 33060644, 2020).
viral meningitis (7 papers, 2012 to 2025). Inflammation of the membranes surrounding the brain and spinal cord due to a viral infection. "The measurement of IL-6 in the CSF and serum is potentially a very useful diagnostic tool for differential diagnosis of bacterial and viral meningitis." (PMID 23483792, 2012). "IL6 level in CSF and serum is useful diagnostic tool for differential diagnosis of bacterial and viral meningitis." (PMID 23483792, 2012). "The measurement of IL-6 in the CSF and serum in potentially a very useful diagnostic tool for differential diagnosis of bacterial and viral meningitis." (PMID 23483792, 2012). "Previous studies have found increased levels of inflammatory cytokines and chemokines in the CSF of patients with viral meningitis, such as IL‐6, IL‐1b, TNF‐α, IL‐10, CXC family chemokines and growth factors." (PMID 37904697, 2023). "There are some inflammatory mediators in CSF or serum that help to differential diagnosis of bacterial and viral meningitis such as IL6, CRP, Pre- calcitonin, TNF, IL8." (PMID 23483792, 2012). "In one study in 1992, IgE, and IL6 was measured in CSF and serum of patients with bacterial and viral meningitis." (PMID 23483792, 2012). "The comparison of IL6 CSF concentration in these two groups (Bacterial and viral meningitis) of children, by use of Mann - Whitney test, show that difference is significant (P < 0.001)." (PMID 23483792, 2012). "Determination of some inflammatory mediators’ example IL-6 and HS-CRP were useful in differential diagnosis of bacterial and viral meningitis." (PMID 23483792, 2012). "Therefore we measured these two mediators (IL6 and HS-CRP) in CSF and serum of children to differentiate bacterial from viral meningitis to prevent severe complications." (PMID 23483792, 2012). "Finally, inflammatory mediators’ example of IL-6 and HS-CRP are useful in differential diagnosis of bacterial and viral meningitis." (PMID 23483792, 2012).
vivax malaria (7 papers, 2012 to 2022). "The aim of this study was to investigate the relationship between single nucleotide polymorphisms (SNPs) in the DDX39B, TNF and IL6 genes and the clinical outcomes of patients with Plasmodium vivax malaria." (PMID 25038626, 2014). "Given the major role of the host immune system in P. vivax infection, the aim of this study was to determine whether mutations in the DDX39B, TNF and IL6 genes were associated with the clinical outcomes of patients with vivax malaria." (PMID 25038626, 2014). "In addition, the genotype combinations GC/CC/GG/GG and GG/CT/GG/GG, corresponding to the respective polymorphisms DDX39B-22/DDX39B-348/TNF-308/IL6-176, were associated with a decreased or increased risk, respectively, of developing mild vivax malaria, probably by altering TNF and IL-6 levels." (PMID 25038626, 2014). "In the present study, vivax malaria patients have shown significant low RANTES/CCL5 levels, but just weakly associated with IL-6, IL-12p40, IFN-γ or MCP-1/CCL2." (PMID 28118834, 2017). "In vivax malaria, IL-6 was inversely correlated with ADAMTS13 activity (ρ = −0.40, P = 0.013) and platelet nadir (r = −0.44, p = 0.0009)." (PMID 25569250, 2015). "The SNPs were assessed regarding association with systemic levels of TNF, IL-6, CXCL10, and CRP, which have been associated with vivax malaria manifestations." (PMID 25038626, 2014). "Because IL-10 regulates the production and function of inflammatory cytokines, we computed IL-10/TNF-α, IL-10/IFN-γ and IL-10/IL-6 ratios and found a bias toward regulatory cytokines in clinical vivax malaria." (PMID 22973442, 2012). "The significance of IL-6 and IL-10 has been highlighted during vivax malaria." (PMID 28118834, 2017). "IL-6, elevated in vivax malaria, is known to be a major inhibitor of ADAMTS13 activity." (PMID 25569250, 2015). "This is the first study to describe patients with DDX39B and IL6 SNPs who had vivax malaria." (PMID 25038626, 2014). "Previous studies have associated the role of BAT1 as an anti-inflammatory gene in diseases such as Chagas cardiomyopathy and Plasmodium vivax malaria through the modulation of tumor necrosis factor-alpha (TNF-α) and interleukin-6 (IL-6)." (PMID 36505884, 2022). "Patients with HBV monoinfection presented the same number of variables which concentrations were increased (mainly IFN-γ, TNF-α, IL-6 and CXCL9), when compared to asymptomatic vivax malaria monoinfection, but only significant decrease of one variable (also IL-4)." (PMID 31233500, 2019). "When compared to symptomatic vivax malaria patients, coinfected individuals presented elevated levels of IFN-γ, IL-10 and CCL2, and diminished plasma concentrations of multiple variables as TNF-α, IL-6, IL-12, and CRP." (PMID 31233500, 2019). "Median concentrations of IL-6 and IL-10 were higher in severe and non-severe vivax malaria compared to controls." (PMID 25569250, 2015). "Furthermore, highly secreted pro-inflammatory cytokines, IL-6 and TNF, in vivax malaria patients represent T cell differentiation toward Th2 and Th17 may be skewed and trigger the natural acquisition of cellular memory immune responses." (PMID 34183015, 2021). "Furthermore, we showed that the predominantly anti-inflammatory cytokine response in clinical vivax malaria was short-lived, with IL-10 concentrations and IL-10/TNF-α, IL-10/IFN-γ and IL-10/IL-6 ratios all returning to within the normal range found in non-infected controls after chemotherapy." (PMID 22973442, 2012).